MTOR (mechanistic target of rapamycin kinase)
Diseases named in the same sentence as MTOR in open-access papers (continued):
Sharing a sentence is not in itself a finding about the gene and the disease.
COVID-19 (continued). "Moreover, the mTOR inhibitors could mitigate the immune response hyper-activation associated with the inflammatory phase of COVID-19." (PMID 38807049, 2024). "Therefore, the upregulation of mTOR pathways may contribute to the anti-inflammatory effects of corticosteroids in patients with high-risk COVID-19." (PMID 36941461, 2023). "Although the mTOR signaling pathway clearly contributes to COVID-19 pathophysiology, its regulatory mechanisms remain incompletely understood." (PMID 41282609, 2025). "The link between mTOR and COVID-19-driven hyperinflammation has been investigated in previous studies." (PMID 40177636, 2025). "In the current study, we found differential expression of genes related to the mTOR pathway in myeloid cells from COVID-19 patients." (PMID 40177636, 2025). "Compared to healthy volunteers, we found that mainly in classical monocytes from the COVID-19 patients, the mTOR pathway-related genes were differentially expressed." (PMID 40177636, 2025). "Of note, the levels of an essential downstream effector of mTOR signaling, ribosomal subunit protein S6 (Rps6), were downregulated in most of the clusters in hospitalized or severe COVID-19 samples pointing toward decreased ribosomal biogenesis." (PMID 40177636, 2025). "In the present study, using single-cell RNA sequencing of circulating immune cells, we found that the mammalian target of rapamycin (mTOR) pathway plays a critical role in myeloid cell regulation in COVID-19 patients." (PMID 40177636, 2025). "Toward this aim, we identified cell type-specific differentially expressed genes (DEGs) from the mTOR pathway between these four independent COVID-19 patient cohorts, for which scRNA-seq data of immune cells were available." (PMID 40177636, 2025). "In this meta-analysis, the severity and mortality outcomes of COVID-19-infected kidney transplant patients were examined in relationto the use of mTOR inhibitors as immunosuppressive drugs." (PMID 40978637, 2025). "Impaired mTOR signaling also became apparent in COVID-19 patients through which SARS-CoV-2 regulates their life cycle and modulates inflammation." (PMID 38365632, 2024). "mTOR pathway-inhibiting drugs also demonstrated their efficacy as potential therapeutic agents for COVID-19." (PMID 38365632, 2024). "Our study integrates p70S6K into the intricate network of mTOR/S6K signaling, underscoring its relevance and potentially offering new insights and therapeutic strategies for managing COVID-19." (PMID 39513867, 2024). "This study is the first to investigate COVID-19 vaccine hesitancy, vaccine safety and efficacy, and the effect of mTOR inhibitors on COVID-19 symptoms in LAM patients during the Omicron pandemic." (PMID 38956624, 2024). "The KEGG results showed that antigen processing and presentation, primary immunodeficiency and viral myocarditis were upregulated in ICU COVID-19 group, while drug metabolism cytochrome P450 and MTOR signaling pathway were downregulated." (PMID 38600309, 2024). "Moreover, mTOR inhibitors may exacerbate the hematologic effects and pneumonia caused by COVID-19." (PMID 38589827, 2024). "It was proposed that mTOR inhibitor can exert favorable therapeutic effects on severe COVID-19 patients by augmenting autophagy along with inhibiting viral replication." (PMID 38979496, 2024). "Our studies previously indicated a possible implication of the AKT/mTOR pathway in severe manifestations of COVID-19." (PMID 39439795, 2024). "Studies indicate that the phosphatidylinositol 3-kinase/protein kinase B/mTOR pathway is dysregulated in COVID-19 patients, affecting their immune response." (PMID 38956624, 2024). "Hyperactivation of PI-3K/Akt/mTOR signaling pathway has also been reported in patients with COVID-19." (PMID 38979496, 2024). "Temporary suspension of anti-metabolite or mTOR immunosuppressants created a window to produce anti-COVID-19 antibodies effectively when an mRNA vaccine was administered." (PMID 36992386, 2023).
COVID-19 (continued). "We have also noticed synergistic OA- and COVID-19-promoting effects of MTOR, a major negative regulator of autophagy." (PMID 38020136, 2023). "Quercetin has been reported to influence SARS-CoV-2 infection and COVID-19-associated cancer progression via suppression of HIF-1a and mTOR." (PMID 37704909, 2023). "We previously demonstrated that mTOR-inhibitors can have a potentially beneficial effect as modulators of immune response to COVID-19 vaccine in KTRs." (PMID 37458909, 2023). "We found diverse signaling pathways and activation pathways associated with COVID-19 subsets, which were enriched in IL2/STAT5, PDGF, and mTOR signaling." (PMID 36992700, 2023). "Some studies have reported the use of rapamycin and other mTOR for calming down cytokine storms and preventing progression of COVID-19." (PMID 35730039, 2022). "PAK signalling (z-score = − 2.53; BH p-value = 4.266 × 10–02) and mTOR signalling (z-score = − 0.632; BH p-value = 4.467 × 10–08) pathways were both found to be downregulated in moderate COVID-19." (PMID 35844004, 2022). "Some reviews suggest the therapeutic potential of mTOR inhibitors, such as rapamycin, against COVID-19 both in vitro and in vivo." (PMID 35801204, 2022). "Metformin can also be involved in the development of COVID-19 by inhibiting the mTOR signaling pathway and altering the composition of the gut microbiota." (PMID 35047039, 2022). "In this report, we analyzed molecular pathways of SARS-CoV-2 infection in Vero E6 cells and COVID-19 patients’ samples to evaluate the balance between the mTOR signaling pathway and the process of autophagy and their correlation with the infection." (PMID 36661509, 2022). "Second, metformin suppresses SARS-CoV-2 infectivity and COVID-19 mortality by inhibiting the mTOR signaling pathway." (PMID 35721716, 2022). "Another prominent drug target gaining interest in the pathophysiology of COVID-19 is the mechanistic target of rapamycin (mTOR) pathway." (PMID 35456985, 2022). "It is known that hyperactivation of mTOR signaling is present in comorbidities considered most prevalent in deceased COVID-19 patients and advanced-age patients." (PMID 36661509, 2022). "Several enzymes can be used as a target for COVID-19 therapeutics including PI3K ̧ mTOR, growth factor receptor, RAF, MAP2K2, FLT3, AXL, AKT, and matrix metalloprotease MMP2 and MMP9." (PMID 35251015, 2022). "L-tryptophan is a metabolic node where many different pathways are gathered, like the regulation of angiotensin-converting enzyme 2 (ACE2), mammalian target of rapamycin (mTOR) activation, both related to COVID-19, and cell proliferation and survival." (PMID 35844615, 2022). "Thereby, various drugs are suggested and used to treat SARS-CoV-2 infection and COVID-19 pathogenesis like sapanisertib, metformin, rapamycin, and rapalog (everolimus), which target the mTOR-signaling pathway." (PMID 34179893, 2021). "At the same time, PI3K/AKT/mTOR inhibitors, such as rapamycin, are potent anti-inflammatory and immunosuppressive agents that can offer therapeutic benefits against COVID-19." (PMID 33920748, 2021). "Sirolimus (or rapamycin), an immunosuppressant and an mTOR inhibitor, is currently undergoing investigation in several clinical trials in COVID-19 patients (NCT04371640, NCT04341675, NCT04461340)." (PMID 34112877, 2021). "In contrast, in KT recipients with symptomatic COVID-19, the most frequently used approach was the suspension of the ADs or mTOR inhibitors, regardless the fact that both these IS drugs showed in vitro antiviral effects against some type of coronavirus." (PMID 33946462, 2021). "On the other hand, possible interactions between CNIs or mTOR inhibitors and antiviral drugs commonly used against COVID-19, such as lopinavir or ritonavir, have been well demonstrated; hence, a strict monitoring of these IS drugs is mandatory." (PMID 33946462, 2021).
COVID-19 (continued). "Although some clinicians do not recommend the use of tacrolimus for SOT recipients with symptomatic COVID-19, a study on liver transplant patients showed that tacrolimus has more protective potential than CyA, mTOR inhibitors, and MPA." (PMID 34681278, 2021). "Some in vitro studies reported that the mTOR-related pathway plays an important role in the modulation of COVID-19 outcomes." (PMID 34578460, 2021). "Overall, the beneficial effects of everolimus on mTOR-mediated autophagy activation must be cautiously evaluated alongside with its effects on host immune system, when treating COVID-19 patients." (PMID 34054782, 2021). "mTOR inhibitors have been proposed to encompass a potential anti-COVID-19 effect by hindering the effect of IL-37 and IL-38 in the inflammatory state." (PMID 33491531, 2021). "In another study, the use of MMF and mTOR inhibitors was held in solid organ tissue recipients with COVID-19, while TAC doses were diminished." (PMID 34692845, 2021). "Although MPAs and mTOR have partial antiviral effects, the current research results do not recommend the use of these drugs for kidney transplant patients with COVID-19." (PMID 34681278, 2021). "Noteworthy, another rationale for using mTOR inhibitors in therapy for COVID-19 is derived from the original field of their medical application, which is the prevention of allotransplant rejection by inhibiting immune responses against foreign antigens." (PMID 33343386, 2020). "The ongoing phase I (SirCo-1, NCT04371640), phase II (The SCOPE trials, NCT04341675) and phase III (NCT04409327) trials that target mTOR in the severe COVID-19 patients will provide more information." (PMID 32691695, 2020). "Currently, two clinical trials using the mTOR inhibitor Sirolimus to treat COVID-19 patients are ongoing." (PMID 32724296, 2020). "Having a contrary action to CQ/HCQ use, also, mTOR inhibitors have been proposed as antiviral drugs in COVID-19, but data on treated patients are limited and results from clinical trials are not available." (PMID 32724296, 2020). "A recent study showed a disruption of mTOR signalling with increased levels of mTOR and a down-regulation of eIF2 signalling in multiple cellular compartments of severe COVID-19 patients when compared to patients who recovered." (PMID 33292691, 2020). "It would therefore be interesting to investigate the effect of CNIs, mTOR inhibitors and thiopurine analogues on the viral replication of COVID-19." (PMID 32982743, 2020). "Random-effects models showed that mTOR inhibitors were significantly associatedwith reduced mortality (OR=0.63, 95% CI 0.48-0.83, P=0.001) but not with COVID-19 severity (OR=0.70, 95% CI 0.41-1.20, P=0.865)." (PMID 40978637, 2025). "In the context of COVID-19,mTOR inhibitors may interfere with the replication and spread of the SARS-CoV-2 virus, leading to a milder infection and improvedoutcomes in kidney transplant patients." (PMID 40978637, 2025). "mTOR inhibitors, AZT, and MMF can induce cytopenia, which could worsen the course of infection since lymphopenia is a parameter associated with severe COVID-19." (PMID 40007028, 2025). "However, this association may be confounded by indication bias and patient selection, as mTOR inhibitors are frequently prescribed for recipients with underlying comorbidities such as chronic kidney disease or CAV—conditions that themselves have been associated with poorer COVID-19 outcomes." (PMID 40808960, 2025). "Furthermore, global studies have reported that inhibition of mTOR can suppress viral replication and growth, highlighting its potential as a therapeutic target in COVID-19." (PMID 41282609, 2025). "In addition, mTOR has been shown to exert potent anti-inflammatory effects, reducing lung inflammation and potentially preventing COVID-19 progression." (PMID 41282609, 2025). "COVID-19 incidence was 33% in the mTOR group versus 36.7% in the non-mTOR group (p = 0.52)." (PMID 41600794, 2025).
COVID-19 (continued). "The PI3K/Akt/mTOR pathway is considered a possible target for the treatment of COVID-19." (PMID 39351097, 2024). "Notably, a large international survey who analyzed the management of the immunosuppressive treatment in several LTx centers showed that most clinicians had continued calcineurin inhibitors and mTOR inhibitors in their patients diagnosed with COVID-19." (PMID 38807049, 2024). "In this study, we found that PTEN and mTOR could be potential targets for metformin in the treat COVID-19/LUAD." (PMID 38811809, 2024). "Inhibitors targeting the PI3K/Akt/mTOR pathway show anti-RNA viral effects, which could be therapeutic for COVID-19." (PMID 38956624, 2024). "It has been suggested that the mTOR pathway is essential for the replication of SARS-CoV-2, and mTOR inhibitors and modulators like sapanisertib and metformin, respectively, may reduce COVID-19 severity." (PMID 37796433, 2023). "The PPI network analysis exhibits that numerous genes, including IL-6, TNF-α, MAPK3, MAPK1, AKT1, mTOR, HIF1A, HSP90AA1, EGFR, CASP3, etc., are implicated in the pathogenicity of COVID-19 disease and also in the anti-COVID-19 effects of Meliae cortex’s key active phytonutrients." (PMID 36817449, 2023). "The adjacent immunosuppressant, mycophenolate–mofetil or mTOR inhibitor, was either halved in 18 (19.1%), minimized in 28 (29.8%), withheld in 20 (21.3%) or left unchanged in 27 (28.7%) participants depending on the COVID-19 severity." (PMID 37632118, 2023). "Another theory shows that SARS-CoV-2 disease downregulates ACE2, resulting in decreased activation of the mammalian target of rapamycin (mTOR) and increased autophagy, resulting in intestinal dysbiosis, diarrhea, and other sympotoms." (PMID 38455085, 2023). "SARS-CoV-2-induced activation of the PI3KCA/AKT/mTOR pathway increases inflammation and reduces immune responses, which may contribute to the severity of COVID-19." (PMID 37547597, 2023). "The cytokine storm in COVID-19 was caused by cross-reactive antibodies that could result in ADE, and inhibitors like rapamycin (an mTOR inhibitor) can be recommended as treatments due to their negative effects on memory B cell activation." (PMID 37515055, 2023). "More importantly, small molecule inhibitors targeting AKT and mTOR and engineered extracellular vesicles encapsulated microRNA targeting mTOR are able to significantly antagonize SARS-CoV-2 infection, highlighting that inhibition of mTOR represents a feasible strategy for preventing COVID-19." (PMID 35938153, 2022). "Several studies have supported this hypothesis that using natural and semisynthetic compounds inhibiting the mTOR signaling is beneficial in suppressing the COVID-19-related complications." (PMID 35455977, 2022). "Findings demonstrated similar infection rates between patients actively on mTOR inhibitors and those who were not, suggesting that mTOR inhibitors do not increase the risk of symptomatic COVID-19." (PMID 35836441, 2022). "Suppression of the mTOR signaling pathway may contribute to the impaired antigen presentation of DCs in COVID-19 patients." (PMID 35265087, 2022). "Immunoregulation with mTOR inhibitor or leucine-rich repeat kinase inhibitor might also alleviate COVID-19 severity by halting cytokine storm." (PMID 35672318, 2022). "This lead us to believe that the balance between mTOR and autophagy could link comorbidities to severe COVID-19 symptoms." (PMID 36661509, 2022). "Preclinical studies and observational findings in KTRs suggest that the mTOR inhibitor sirolimus may enable enhanced immunological responses to COVID-19 vaccination, as compared to standard of care immunosuppression which includes mycophenolate." (PMID 36109788, 2022). "In addition, the most significant KEGG pathways were enriched for overlapping DEGs in COVID-19 patients, including human immunodeficiency virus 1 infection, apoptosis, the mTOR signaling pathway and TNF signaling pathway." (PMID 35755819, 2022).
COVID-19 (continued). "Similarly, Rapamycin and other mTOR inhibitors, which block translation, are in trials as post-exposure prophylaxis for COVID-19, to prevent the early stage of severe disease from progressing." (PMID 35165389, 2022). "The “SARS-COV-2–human PPI network” constructed in this study, indicates that mTOR may be a potential key target of COVID-19, and its inhibitors may elicit curative anti-SARS-COV-2 effects." (PMID 36210820, 2022). "Additionally, there are convincing reasons available to repurpose mTOR inhibitors for use in COVID-19 due to their immunomodulatory and antiviral properties." (PMID 36233149, 2022). "Recent studies have shown that mTOR’s protein-protein interaction could also be anti-COVID-19; consequently, the anti-mTOR rapamycin’s use might be adjusted." (PMID 35371880, 2022). "However, further studies are critically needed to evaluate and consider consequences of using mTOR drugs as rapamycin against COVID-19." (PMID 35730039, 2022). "The therapeutic potential of mTOR inhibitors for COVID-19 has been reported." (PMID 36210820, 2022). "However, at the same time, mTOR inhibitors can induce leukopenia, thrombocytopenia, and pneumonitis, therefore possibly further worsening the hematological effects of COVID-19." (PMID 33946462, 2021). "In contrast, in KT recipients with symptomatic COVID-19, suspension of ADs or mTOR inhibitors was adopted in up to 79% of patients, especially in those patients requiring invasive ventilation, while CNI withdrawal (31.87%) was reserved in those who were severely symptomatic." (PMID 33946462, 2021). "However, the only research focus on the PI3K/Akt/mTOR/HIF-1α in COVID-19 pathogenesis is in contradiction to the evidence of overexpressed HIF-1α in other studies." (PMID 34277453, 2021). "Inhibitors to the Akt/mTOR/HIF-1 signaling are also promising in treating COVID-19." (PMID 34277453, 2021). "For asymptomatic patients or those with mild COVID-19 symptoms, a “wait and see approach” was mostly used; a suspension of antimetabolites drugs (347/461, 75.27%) or mTOR inhibitors (38/48, 79.2%) was adopted in the majority of patients with symptomatic COVID-19 infections." (PMID 33946462, 2021). "However, additional studies are necessary to further elucidate the exact role of mTOR inhibitors and modulators in the treatment of COVID-19." (PMID 34671273, 2021). "Use of sirolimus in a patient with renal transplant recipient helped in preventing intensification of the severity in COVID-19 attributing to its inhibiting effect on mammalian target of rapamycin (mTOR) which he was using post his renal transplant, therefore, proving to be a blessing in disguise." (PMID 34527488, 2021). "Naturally existing compounds (phytochemicals) through their actions on endolysosomes and mTOR signaling pathways might provide therapeutic relief against COVID-19." (PMID 33768214, 2021). "Among these candidates, Sirolimus, which consists of an mTOR inhibitor and dactinomycin, may be a potential drug for COVID-19 treatment." (PMID 34690930, 2021). "Metformin, an FDA-approved mTOR inhibitor, when administered as an anti-hyperglycemic drug in diabetes patients, was found to simultaneously act as an anti-hyperglycemic and antiviral agent, offering benefits in patients with COVID-19." (PMID 34671273, 2021). "Thus, further study is still required to clarify the role of PI3K/Akt/mTOR pathway in regulating HIF-1α expression in COVID-19." (PMID 34277453, 2021). "This choice could be due to the pulmonary toxicity associated with mTOR-Is or to a possible interaction between mTOR-Is and antiviral drugs commonly used in COVID-19 patients." (PMID 34497515, 2021). "In COVID-19, the mTOR pathway may provide valuable targets for controlling cell injury, oxidative stress, impaired autophagy and onset of hyperinflammation." (PMID 33361522, 2020).